CDH5 (cadherin 5)
Diseases named in the same sentence as CDH5 in open-access papers (continued):
Sharing a sentence is not in itself a finding about the gene and the disease.
lung carcinoma (continued). "In this study, we studied the association of CDH5 expression with common EGFR mutations (exon 19 delE746-A750 and exon 21 L858R) in lung cancer cells and mouse xenograft models." (PMID 27362942, 2016). "Further studies show that expression of CDH5 is decreased after the inhibition of EGFR and downstream Akt pathways in lung cancer cells with EGFR mutation." (PMID 27362942, 2016). "After inhibition of the phosphorylation of Akt, downregulation of CDH5 protein was also observed in the lung cancer cells studied." (PMID 27362942, 2016). "Further inhibition of the Akt pathway showed decreased expression of CDH5 in EGFR mutant lung cancer cells." (PMID 27362942, 2016). "The expression of CDH5 was evaluated in tumors of A549 lung cancer stable cells using IHC study." (PMID 27362942, 2016). "In addition, mutant EGFR genes potentiates angiogenesis in lung cancer cells, which is inhibited by CDH5 siRNA, and potentiates migration and invasion in lung cancer cells." (PMID 27362942, 2016). "Increased expression of CDH5 is related to increased angiogenesis in lung cancer cells." (PMID 27362942, 2016). "Since CDH5 has been reported to be a potential target for cancer therapy, our results may also contribute to the future development of anti-CDH5 therapy in conjunction with EGFR-TKI therapy in lung cancer patients." (PMID 27362942, 2016). "Together with our findings, CDH5 may also contribute to an increased lung cancer metastasis." (PMID 27362942, 2016). "The expressions of CDH5 mRNA and protein were detected in mutant and wild type EGFR genes transfected stable lung cancer cells." (PMID 27362942, 2016). "CDH5, which is upregulated in exon 19 deletion mutant EGFR gene overexpressed lung cancer cells, is related to the ability of metastasis in lung cancer cells." (PMID 27362942, 2016). "The levels of transmembrane protein 143, cadherin 5, fibronectin 1, and collectin-11 decreased significantly in the serum of patients with metastases compared with those of nonmetastatic lung cancer patients." (PMID 33728331, 2021). "Interestingly, some incoming signaling pathways were found to be specific to one subtype of lung cancer, as exemplified by HGF (a new highlight in the treatments of lung cancer), KIT (activating the JAK/STAT and PLC/PKC signaling pathways) in LUAD, and the CSF3 and CDH5 in LUSC." (PMID 36008393, 2022). "CLDN10-AS1 might play a role in the development and progression of lung cancer, by regulating the G1/S transition of mitotic cell cycle through miR-125b-5p/PPAT and by regulating endothelium development, angiogenesis, and cell-cell adherens junction through miR-125b-5p/CDH5, respectively." (PMID 32149133, 2020).
Hyperglycemia (17 papers, 2014 to 2024). An increased concentration of glucose in the blood. "For hyperglycemia, specific DEMs including cadherin-5 (CADH5) 28, corticosteroid-binding globulin (CBG) 29, and a polypeptide from serotransferrin (TRFE) 30 have been reported to be associated with either elevated blood glucose, T2D or insulin resistance." (PMID 32089734, 2020). "Expression of CDH5, CTNNB1, and PRKCB was checked in the hyperglycemia disease model, and we observed that PRKCB was localized extensively in the membrane, while the signals of CDH5 and CTNNB1 were diffused and not exclusively on the membrane." (PMID 34180064, 2021).
Stroke (16 papers, 2016 to 2026). Sudden impairment of blood flow to a part of the brain due to occlusion or rupture of an artery to the brain. "To this end, we generated 3-month-old VE-cadherin-Cre (Cdh5-Cre) transgenic mice to explore the impact of BMVECs FPN1 in brain iron homeostasis after stroke." (PMID 36841833, 2023). "Complementary experimental stroke studies were performed using transient and permanent middle cerebral artery occlusion (MCAo) in wild-type mice and in endothelial-specific RiboTag mice (Cdh5^Cre-ER(T)) that enable selective isolation of endothelial mRNA." (PMID 42277837, 2026).
Hypertension (15 papers, 2017 to 2025). The presence of chronic increased pressure in the systemic arterial system. "The present results in Cdh5-CreERT-Nox2KO mice and Tie2-Nox2KO mice clearly establish that endogenous endothelial Nox2 augments AngII-induced hypertension, at least in the relatively short term (2 weeks)." (PMID 28298457, 2017). "AngII-induced hypertension, however, was significantly attenuated in Cdh5-CreERT2-Nox2KO mice (Figure IIIC in the online-only Data Supplement), pointing to endothelial Nox2 as a crucial player in AngII-mediated hypertension." (PMID 28298457, 2017). "AP-2αflox/flox/CDH5-Cre-ERT2 mouse was injected with tamoxifen to induce endothelium-specific AP-2α gene knockout, which was followed by lovastatin administration prior to hyperlipidemia and hypertension." (PMID 38580662, 2024).
colorectal cancer (11 papers, 2009 to 2025). A primary or metastatic malignant neoplasm that affects the colon or rectum. "Additionally, ST3GAL6-AS1 was co-expressed with a variety of mRNAs, including PECAM1, VCAM1, CXCL12, CD34, CDH5, and VWF, and was associated with colorectal cancer progression." (PMID 33790949, 2021).
gastric cancer (11 papers, 2014 to 2025). A primary or metastatic malignant neoplasm involving the stomach. "Correlation between CDH5 expression with clinicopathological parameters of gastric cancer patients (n=75) from gastric cancer tissue microarrays." (PMID 39172098, 2024). "In this study, we showed that Notch1 could regulate CDH5 expression by targeting CDH5 promotor, providing insight into how Notch1 upregulation enhanced the proliferation, migration, invasion, and vasculogenic mimicry capacity of gastric cancer cells." (PMID 39172098, 2024). "Also, the promoter region hypermethylation of Dkk-3, CDH-5, DDAPK, p16, and RASSF1A genes are individual biomarkers useful in predicting the clinical features of gastric cancer patients." (PMID 28144288, 2017).
myocardial infarction (9 papers, 2017 to 2025). Gross necrosis of the myocardium, as a result of interruption of the blood supply to the area, as in coronary thrombosis. "Mesenchymal transcript expression in Cdh5-traced cells returns to levels detected in homeostasis condition after more than 10 days post-myocardial infarction." (PMID 33514719, 2021).
preeclampsia (9 papers, 2020 to 2026). Preeclampsia is a hypertensive disorder of pregnancy that is characterized by new-onset hypertension with proteinuria presenting after 20 weeks of gestation, and depending on mild or severe forms may initially present with severe headache, visual disturbances, and hyperreflexia. "ITGA1 and CDH5 play key roles in CTB differentiation and have potential disease associations (e.g., preeclampsia)." (PMID 32493340, 2020).
uveal melanoma (8 papers, 2009 to 2025). A melanoma derived from melanocytes of the uveal tract. "Using a Venn diagram with TCF-4 co-expressed genes versus CDH5 co-expressed genes, 7 genes were robustly correlated, being S1PR1 the most prominent one not only in uveal melanoma but also in cutaneous melanoma." (PMID 36797281, 2023).
metastatic melanoma (7 papers, 2015 to 2023). A melanoma that has spread from its primary site to another anatomic site. "In BALB/C nude mice xenografted metastatic melanoma C8161 cell, jatrorrhizine (50 μg) reduced neovascularization of tumor, probably due to its suppression of CDH5 expression, which encodes the vascular endothelial cadherin." (PMID 35095493, 2021).
coronary artery disease (6 papers, 2009 to 2026). "Thus, it may indicate that the rs7404339 polymorphism in CDH5 has a significant effect on coronary artery disease of KD by changing the expression of VE-cad." (PMID 35571208, 2022). "Plasma exosomes from patients with coronary artery disease were found to suppress cadherin-5 in human aortic endothelial cells, negatively impacting vascular permeability and causing aggravated atherosclerotic lesions." (PMID 41596469, 2026).
ischemia (6 papers, 2019 to 2024). A hypoperfusion of the BLOOD through an organ or tissue caused by a PATHOLOGIC CONSTRICTION or obstruction of its BLOOD VESSELS, or an absence of BLOOD CIRCULATION. "Under nonischemic conditions, pericytes expressed Cdh19, Cdh6, Cdh10, Cdh4, Cdh13, and Cdh5; after ischemia, the cadherin genes that were predominantly expressed were Cdh15, Cdh11, Cdh3, and Cdh2." (PMID 33726849, 2021). "Four hours after ischemia onset, neocortical mRNA levels of all analyzed genes except VE-cadherin (Cdh5) were significantly down-regulated by about 50%, whereat the fold change ranged between 0.55 for α-catenin 2 (Ctnna2) and 0.38 for N-cadherin (Cdh2)." (PMID 31089963, 2019).
ischemic stroke (6 papers, 2020 to 2026). A stroke disorder caused by obstruction of blood flow to the brain, due to thrombotic (local blood clot formation) or embolic (due to a blood clot or other material traveling from another site) event. "To understand how Rab7a affects the disassembly of BBB tight and adherens junctions during the acute phase of ischemic stroke, we analyzed the morphology of eGFP::Claudin-5+, ZO-1+ TJs and CDH5+ AJs at 48 hours after t-MCAO by immunofluorescence and electron microscopy." (PMID 41024170, 2025).
leukemia (6 papers, 2012 to 2024). A malignant (clonal) hematologic disorder, involving hematopoietic stem cells and characterized by the presence of primitive or atypical myeloid or lymphoid cells in the bone marrow and the blood. "We further injected 10,000 B-ALL cells together with 2 × 105 total BM cells into lethally irradiated recipients, including Cdh5-Cre;Vps33bfl/fl, Prx1-Cre;Vps33bfl/fl and Pf4-Cre;Vps33bfl/fl mice, and monitored the effects on leukemia development." (PMID 37751067, 2024).
metastatic tumors (6 papers, 2013 to 2025). "The ROC analyses, even performed on a limited number of samples, identified the cut-off levels of CDH1, CDH5, and ZEB1 genes useful for the possible diagnostic identification of primary or metastatic tumors." (PMID 40332096, 2025). "Elevated CDH5 levels (P=0.028) and ratios of CDH5:HPA binding (P=0.007) distinguished patients with metastatic disease from those that remained metastasis-free." (PMID 27010749, 2016).
angiosarcoma (5 papers, 2013 to 2022). A malignant tumor arising from the endothelial cells of the blood vessels. "To address whether direct targeting of adult endothelial cells would result in the development of angiosarcomas with higher efficiency we used the Cdh5-CreERT2 mouse." (PMID 31221668, 2019). "In addition to including various vascular endothelial markers (ECSCR, TIE1, CD34, CDH5, ESAM), the angiosarcoma gene signature also included ROS1, supporting a possible broader role of ROS1 in the pathogenesis of this disease." (PMID 23637631, 2013).
chronic kidney disease (5 papers, 2018 to 2024). Impairment of the renal function secondary to chronic kidney damage persisting for three or more months. "Interestingly, in renal I/R injury, endothelial-specific Phd2 ablation (Cdh5-Cre) was protective, preserving kidney function and preventing the transition from acute kidney injury (AKI) to chronic kidney disease (CKD) in a HIF-1-dependent manner." (PMID 38509356, 2024).
hyperlipidemia (5 papers, 2022 to 2024). "Endothelium-specific deletion of Txndc5 also markedly increased eNOS expression in the ligated LCA in Txndc5∆ECKO, compared with that in control (Cdh5-Cre/ERT2), mice with hyperlipidemia induced by PCSK9 overexpression and HFD." (PMID 35061532, 2022).
Lipedema (5 papers, 2022 to 2026). Disorder of adipose tissue characterized by symmetric and bilateral enlargement of the lower extremities due to abnormal deposition of subcutaneous fat often in obese women. "The authors showed that soluble factors released from cultured lipedema SVF (stromal vascular fraction) cells led to a significant reduction of VE-cadherin (cadherin-5) expression in endothelial cells in an in vitro model." (PMID 36675759, 2022).
lymphedema (5 papers, 2020 to 2025). Excess fluid collection in tissues, causing swelling. "CDH5 has been identified as a potential biomarker for detecting lymphedema and may also be useful in identifying glaucoma patients." (PMID 38287276, 2024).
metastatic cancer (5 papers, 2014 to 2025). A carcinoma which has spread from the original site of growth to another anatomic site. "In particular, CDH5 levels higher than 0.135 and 0.1865 significantly distinguished between healthy and cancer cells and primary vs. metastatic cancer cells, respectively." (PMID 40332096, 2025). "Interestingly, we found that the expression levels of CDH1, which encodes the epithelial marker E-cadherin, CDH5, encoding vascular endothelial cadherin, and the epithelial-to-mesenchymal transition-transcription factor ZEB1, effectively distinguished primary from metastatic cancer cells." (PMID 40332096, 2025). "Interestingly, CDH5, CDH17, and L1CAM share their involvement in several metastatic cancers, which could be related to the pairwise sequence alignment found near the RGD motif for the combinations CDH17/L1CAM and CDH17/CDH5 (its second RGD motif)." (PMID 41039222, 2025). "Using this approach, cadherin-5 (CDH5) emerged as a novel biomarker for metastatic breast cancer, when assessed by ELISAs that incorporate measurements of glycosylation status, evaluated by binding of the lectin Helix pomatia agglutinin (HPA) known to detect poor prognosis metastatic cancer." (PMID 27010749, 2016).
Cerebral ischemia (4 papers, 2016 to 2024). Restriction of arterial blood supply to the brain associated with insufficient oxygenation to support the metabolic requirements of the tissue. "In the present study, we established a dMCAO model in 3-month-old Cdh5-Cre transgenic mice to generate brain tissue infarction and the consequent reduced blood flow, which is commonly used in animal models of cerebral ischemia." (PMID 36841833, 2023).
coronary atherosclerosis (4 papers, 2014 to 2022). Atherosclerosis of the coronary vasculature. "In cardiovascular research, elevated levels of CDH5 have also been reported to be associated with coronary atherosclerosis." (PMID 31936828, 2020).
glaucoma (4 papers, 2020 to 2024). Increased pressure in the eyeball due to obstruction of the outflow of aqueous humor. "Elucidating the relationship between FUT2, CDH5, and endothelial function in the context of glaucoma may provide valuable insights into the disease’s pathology and open new avenues for targeted therapeutic approaches." (PMID 38287276, 2024). "The role of CDH5, a cadherin involved in vascular and lymphatic maintenance, in glaucoma could further support this speculation." (PMID 38287276, 2024). "Understanding the molecular mechanism linking EndoMT and SC could be crucial for deciphering the role of glaucoma-associated genes like FUT2 and CDH5 and their impact on endothelial function." (PMID 38287276, 2024). "Some of these autoantibodies react with proteins which have previously been associated with glaucoma, such as LOX and TMEM9B, as well as proteins which have little or no previous association with the disease, such as CDH5 and FUT2." (PMID 38287276, 2024). "Recently, it was found to decrease, together with its interaction partners CDH5 and KIT, in fibrotic versus non-fibrotic conjunctival fibroblast cell lines from patients with and without previous glaucoma surgery, respectively (their fig." (PMID 33047019, 2020).
heart failure (4 papers, 2023 to 2026). Inability of the heart to pump blood at an adequate rate to meet tissue metabolic requirements. "To examine whether Scarb1 is actually a critical pathologic gene in mouse heart failure models, we generated EC-specific Scarb1 knockout mice (Scarb1 CKO) by crossing Cdh5-CreERT2 mice expressing EC-specific Cre induced by tamoxifen with Scarb1-flox mice." (PMID 40772900, 2025).
Hypoglycemia (4 papers, 2014 to 2026). A decreased concentration of glucose in the blood. "Under hypoglycemia, decreases in cadherin-5 and soluble angiopoietin-1 receptor (sTie-2) were observed, with increased P-selectin, intercellular adhesion molecule-3 (ICAM3), ANGPT1 and PAI-1." (PMID 41596469, 2026). "Consistent with that study, in the combined cohort, cadherin-5 levels decreased under hypoglycemia and 2 h post hypoglycemia, inferring transient impacts on vascular integrity." (PMID 41596469, 2026). "Post hypoglycemia, decreased cadherin-5 and ICAM5 were observed at 2 h and PAI-1 at 4 h, as well as increases in P-selectin at 30 min, 1 h and 24 h and ICAM3 at 24 h." (PMID 41596469, 2026). "In the combined cohort, upon induction of hypoglycemia, there were significant decreases in cadherin-5 (p = 0.01) and sTie-2 (p = 0.01) and significant increases in P-selectin (p < 0.01), PAI-1 (p < 0.001), ANGPT1 (p < 0.001) and ICAM3 (p = 0.03) compared to baseline." (PMID 41596469, 2026). "In the combined cohort, there were significant decreases in cadherin-5 (p = 0.01) and ICAM5 (p < 0.01) at 2 h and in PAI-1 (p = 0.02) at 4 h post hypoglycemia in both T2D and controls compared to baseline." (PMID 41596469, 2026).